RIPK1 (receptor interacting serine/threonine kinase 1)
Diseases named in the same sentence as RIPK1 in open-access papers (continued):
Sharing a sentence is not in itself a finding about the gene and the disease.
inflammatory bowel disease (29 papers, 2019 to 2025). A spectrum of small and large bowel inflammatory diseases of unknown etiology. "All patients with RIPK1 deficiency presented with early-onset inflammatory bowel disease and decreased serum IgA and IgM levels." (PMID 39072316, 2024). "Biallelic loss-of-function RIPK1 variants, have been linked to severe immunodeficiency, early-onset inflammatory bowel disease and arthritis." (PMID 38676845, 2024). "In humans, rare homozygous loss-of-function (LoF) mutations in RIPK1, including missense, nonsense, and frameshift mutations, cause combined immunodeficiency and inflammatory bowel disease (IBD)." (PMID 39062098, 2024). "The main clinical phenotypes of these RIPK1-deficient patients include early-onset inflammatory bowel disease, polyarthritis, and recurrent viral, bacterial, and fungal infections." (PMID 37083451, 2023). "On one side, the deficiency of RIPK1 is a recessively inherited disease characterized by severe immunodeficiency, arthritis, and early-onset inflammatory bowel disease that is a consequence of biallelic, loss-of-function RIPK1 variants." (PMID 35716229, 2022). "Recently, loss of function mutation of RIPK1 was found in patients with immunodeficiency and inflammatory bowel diseases." (PMID 34462571, 2022). "For instance, patients with biallelic RIPK1 loss-of-function mutations suffer recurrent infections, early-onset inflammatory bowel disease, and progressive polyarthritis." (PMID 34862394, 2021). "The resulting phenotypes of RIPK1-deficiency have been summarised for 16 patients from among 13 families to date, and comprise inflammatory bowel disease (IBD), recurrent viral, bacterial and fungal infections, and, in some cases, progressive, inflammatory polyarthritis." (PMID 39762600, 2025). "Besides the patient mutations of the regulatory caspase 8 cleavage site in RIPK1 (D324A/E/H) we integrated the C601Y missense mutation, which causes immunodeficiency and inflammatory bowel disease, into the reporter." (PMID 39088265, 2024). "But interestedly, Patients with biallelic inactivating mutations in RIPK1, including missense, nonsense, and frameshift mutations, exhibit symptoms of inflammatory bowel disease and combined immunodeficiency, develop lymphopenia, and display increased sensitivity to TNFR1-mediated cell death." (PMID 37090690, 2023). "While, loss of RIPK1 in mice leads to perinatal lethality, homozygous loss-of-function mutations of RIPK1, including frameshift, missense, and nonsense mutations in human individuals, cause severe immunodeficiency, inflammatory bowel diseases, and arthritis." (PMID 39872161, 2022). "Ripk1K612R/K612R mice may provide a good model for studying the mechanism by which reduction of RIPK1 expression in adults leads to inflammatory bowel disease (IBD) as Ripk1-deficient condition in humans." (PMID 33311474, 2020). "Patients with AR RIPK1 deficiency exhibit inflammatory bowel disease (IBD), polyarthritis, and recurrent infections." (PMID 40498270, 2025). "We present the clinical features, genetic analysis and immune work-up of two patients with infantile-onset inflammatory bowel disease (IBD) resulting from RIPK1 mutations." (PMID 36466854, 2022). "RIPK1 inhibitors are promising for treating inflammatory bowel disease, where RIPK1-PANoptosome activation drives epithelial cell death and barrier dysfunction." (PMID 40721869, 2025). "The active RIPK1 and necroptosis have been involved in many human diseases such as multiple sclerosis, myocardial ischemia-reperfusion injury, inflammatory bowel disease and Alzheimer’s disease." (PMID 32075957, 2020). "Although cell type-specific functions of RIPK1 have been investigated using conditional Ripk1 knockout mice, the immune cell type in which RIPK1 functions to protect against inflammatory bowel disease is unknown at present." (PMID 34462571, 2022).
inflammatory bowel disease (continued). "IRF1 upregulates multiple PANoptosome components, including ZBP1, RIPK1, and AIM2, driving PANoptosis in models of inflammatory bowel disease (IBD) and alcoholic liver disease." (PMID 41583472, 2025). "Furthermore, we present robust protocols for detecting human Caspase-8, RIPK1, RIPK3, and MLKL and illustrate their utility for detecting dysregulated necroptosis in biopsies from patients with inflammatory bowel disease (IBD)." (PMID 38750308, 2024).
colon carcinoma (28 papers, 2015 to 2025). "To study how the phospho-mimic mutations S209E and S213E affect necroptosis, we used human colon cancer cells (HT-29) that lack RIPK1 (RIPK1-KO)." (PMID 40715038, 2025). "Nec-1 (Necrostatin-1), a type II inhibitor targeting the RIPK1 allosteric pocket, significantly reduces tumour burden (volume and number) in murine colon cancer models by inhibiting RIPK1 kinase activity and suppressing the JNK/c-Jun pathway." (PMID 41334873, 2025). "IAP inhibitors synergize with IFNγ to activate the RIPK1-dependent cell death pathway in a colon cancer cell model." (PMID 40057483, 2025). "In colon cancer cells, OSW-1 has been demonstrated to cause necroptosis through the RIPK1/RIPK3/MLKL signaling pathway, with this action mediated by the RIPK1-p62/SQSTM1 complex." (PMID 40422233, 2025). "2-methoxy-6-acetyl-7-methyljuglone (MAM) induces necroptosis in colon cancer cells by forming the RIPK1/RIPK3 complex, activating JNK and elevating ROS." (PMID 35884370, 2022). "It has high affinity for RIPK1 and exerts a strong inhibitory effect on it in human colon cancer (HT-29) and mouse fibroblast-like (L929) cells." (PMID 35290562, 2022). "Studies had shown that RIPK1 expression was significantly reduced in colon cancer tissues compared with adjacent normal colon tissues, thus impounding the cancer cell response to programmed necrosis." (PMID 36249746, 2022). "Instead, caspase inhibitors and/or second mitochondria-derived activators of caspase mimetic are needed to sensitize colon cancer cells to RIPK1 and RIPK3." (PMID 35884370, 2022). "We found that mRNA expression of Ripk1 and Ripk3 was significantly decreased in colon cancer tissues compared with paired normal colon tissues (P=0.0039 for Ripk1 and Ripk3 by Wilcoxon matched-pairs signed-rank test)." (PMID 25675296, 2015). "Here we show that RIPK1 and RIPK3 expression is significantly decreased in human colon cancer tissues, suggesting that suppression of RIPK1 or RIPK3 expression is advantageous for cancer growth." (PMID 25675296, 2015). "Another investigation revealed that FA could induce apoptosis and autophagy in HCT116, Caco-2, and HT29 cells in vitro at a concentration of 100–400 nM in tributyltin (IV) ferulate in colon cancer by G2/M cell cycle arrest and downregulate RIPK1 levels." (PMID 40487371, 2025). "Moreover, in colon cancer cells, by cooperating with RIPK1/RIPK3, ROS can facilitate cytosolic calcium accumulation and give rise to striking necroptosis." (PMID 35222645, 2022). "Interestingly, RIPK1 and RIPK3 expression in colon cancer cells is reduced by hypoxia, a hallmark of solid tumor." (PMID 25675296, 2015). "However, in colon cancer, the loss of RIPK1 and RIPK3 expression was found not to be due to epigenetic DNA modification." (PMID 36849530, 2023). "Regarding the expression of the molecular effectors of necroptosis in tumors, some studies reported a decreased expression of RIPK3, but not RIPK1, in AML, while deficiency of both RIPK3/RIPK1 has been reported in colon cancer as compared to non-malignant adjacent tissues." (PMID 34490126, 2021). "Interestingly, transcription of Ripk1 and Ripk3 was controlled by hypoxia, suggesting that hypoxia may be one of the mechanisms that regulate Ripk1 and Ripk3 expression in human colon cancer tissues." (PMID 25675296, 2015). "RIPK1/RIPK3-MLKL signaling molecules are fundamental in initiating necroptotic cell death, but their roles in the development of colon cancer are unclear." (PMID 39540935, 2024). "By contrast, other studies have indicated a marked decrease in RIPK1 and RIPK3 expression in human colon cancer tissues compared to the adjacent normal tissues." (PMID 39540935, 2024). "Instead of targeting the three major proteins, PARP-1, a downstream active effector of RIPK1/RIPK3, can be activated by TRAIL and induce necroptosis in colon cancer cells." (PMID 35884370, 2022).
colon carcinoma (continued). "For instance, mitochondria-derived ROS promoted autophosphorylation of RIPK1, which enabled RIPK1 to recruit RIPK3 to form necrosome (RIPK1/RIPK3), initiating TNFα-mediated necroptosis in colon cancer cells." (PMID 36211509, 2022). "Cobalt chloride and GLTP overexpression rely on RIPK1, RIPK3, and MLKL to induce necroptosis in colon cancer cells." (PMID 35884370, 2022). "To explore the role of necroptosis in chemotherapy-induced cell death, we used inhibitors of RIPK1 or RIPK3 kinase activity, and modulated their expression in colon cancer cell lines using short hairpin RNAs." (PMID 25675296, 2015). "In this study, we found that RIPK1 and RIPK3 expression was reduced in primary colon cancer tissues compared with normal adjacent tissues." (PMID 25675296, 2015). "Indeed, we found that RIPK1 and RIPK3 are largely dispensable for colon cancer cell death induced by many common chemotherapeutic agents." (PMID 25675296, 2015). "We found that chemotherapeutic agents did not effectively elicit RIPK1/RIPK3-dependent necroptosis in colon cancer cells." (PMID 25675296, 2015). "We previously reported that CRISPR/Cas9-mediated knockout (KO) of USP22 in the human colon carcinoma cell line HT-29 affects RIPK3 ubiquitination during necroptosis without inducing major changes in RIPK1, RIPK3, and MLKL gene expression, suggesting gene-specific regulation of USP22." (PMID 35933402, 2022). "Upregulation of RIPK1 has been reported in lung cancer and glioblastoma tissues, but not in colon cancer, suggesting that distinct mechanisms of cell killing may exist in different tumor types." (PMID 27362805, 2016). "However, the loss of RIPK1 and RIPK3 expression in colon cancer was not due to epigenetic DNA modification." (PMID 25675296, 2015).
colorectal cancer (27 papers, 2018 to 2025). A primary or metastatic malignant neoplasm that affects the colon or rectum. "The RIPK1 also interacts with TRAF-6 through the polyubiquitination of Lys48-linked RIPK1, which leads to a reduced level of kinase in colorectal cancer cells." (PMID 41303584, 2025). "For example, TRAF6 directly interacts with RIPK1 via the polyubiquitination of Lys48-linked RIPK1, thus promoting the proliferation of colorectal cancer cells." (PMID 39409087, 2024). "TRAF6 directly interacts with RIPK1 through the polyubiquitination of Lys48-linked RIPK1 and reduces the levels of RIPK1 protein in colorectal cancer cells, leading to necroptosis, thus promoting the proliferation of colorectal cancer cells." (PMID 36604411, 2023). "Polymorphisms of RIPK1 gene have been reported to be associated with multiple myeloma, diffuse large B cell lymphoma, colorectal cancer, and childhood leukemia." (PMID 37996860, 2023). "Our results clearly indicate that low expression of RIPK1 mRNA is significantly associated with higher aneuploidy in breast, lung, and colorectal carcinomas." (PMID 30598363, 2019). "Furthermore, RIPK1-mediated cell proliferation through MCU is a central mechanism underlying colorectal cancer progression." (PMID 41303584, 2025). "While treatment with TNF/SMAC mimetic (SM)/z-VAD-FMK (TSZ) caused time- and RIPK1-dependent necroptosis in human colorectal cancer HT-29 cells, mouse dermal fibroblasts (MDFs) and murine L929 cells, TSZ also triggered ubiquitylation of endogenous MLKL in all these cell types." (PMID 34099649, 2021). "Evidences have suggested RIPK1 polymorphisms could be a possible biomarker in colorectal cancer." (PMID 32272907, 2020). "For example, colorectal cancer cells resistant to apoptosis have been shown to upregulate RIPK1, making them more prone to necroptosis." (PMID 40427552, 2025). "Transient and stable overexpression of TRAF6 in colorectal cancer cells significantly decreased the protein levels of RIPK1 and p-RIPK1 as well as downstream p-RIPK3 and p-MLKL produce inhibition." (PMID 36604411, 2023). "The RIPK1 inhibitor Necrostain-1 inhibits colorectal cancer cell necroptosis via the RIPK1/RIPK3/MLKL signaling pathway." (PMID 36604411, 2023). "Knockdown of TRAF6 in colorectal cancer cells significantly up-regulated the protein levels of RIPK1 and p-RIPK1 and downstream p-RIPK3 and p-MLKL." (PMID 36604411, 2023). "Another study suggested that MCU interacts with RIPK1 to promote colorectal cancer cell proliferation by increasing mitochondrial Ca2+ uptake and energy metabolism." (PMID 37885995, 2023). "In this study, we found that TRAF6 enhances the progression of colorectal cancer cells by inhibiting RIPK1-mediated necroptosis." (PMID 36604411, 2023). "In conclusion, we demonstrated that TRAF6 promotes cancer cell progression by inhibiting necroptosis via RIPK1 in colorectal cancer cells." (PMID 36604411, 2023). "It was then shown that TRAF6 can be significantly linked to RIPK1 by polyubiquitination in HCT116 and SW480 colorectal cancer cells." (PMID 36604411, 2023). "The recent study found that TRAF6 inhibits necroptosis in colorectal cancer cells via the RIPK1/RIPK3/MLKL signaling pathway." (PMID 36604411, 2023). "For example, the activation of the receptor-interacting serine/threonine-protein kinase 1 (RIPK1)/RIPK3/mixed lineage kinase ligand (MLKL)/C-Jun N-terminal Kinase (JNK)/IL-8 pathway can block tumor-cell reaggregation in colorectal cancer after radiotherapy." (PMID 35740953, 2022). "Comparison of their expression in HUVEC and HT-29, a human colorectal carcinoma cell line, revealed that RIPK1 and MLKL were expressed in HUVEC and HT29, while RIPK3 was normally expressed in HT29 but at an extremely low level in HUVEC." (PMID 32332696, 2020). "The upregulation and overexpression of RIPK1 have been confirmed in human colorectal cancer cells." (PMID 41303584, 2025).
colorectal cancer (continued). "However, the interaction of MCU with receptor-interacting protein kinase 1 (RIPK1) can increase mitochondrial Ca2+ uptake, resulting in increased proliferation of colorectal cancer cells." (PMID 35851420, 2022). "Additionally, TRAF6 has been shown to directly interact with RIPK1 via Lys48-linked polyubiquitination, reducing p-RIPK1 levels and inhibiting the activation of the RIPK1–RIPK3–MLKL axis in colorectal cancer cells, thereby suppressing necroptosis and promoting tumour progression." (PMID 41334873, 2025). "Meanwhile, TRAF6 regulates the abundance of RIPK1, inhibits RIPK1/RIPK3/MLKL necrosis signaling pathways and affects the progression of colorectal cancer." (PMID 38169510, 2024). "And FMRP (Protein of FMR1) binds RIPK1 mRNA, suggesting that FMRP acts as a regulator of necroptosis pathway through the surveillance of RIPK1 mRNA metabolism in colorectal cancer." (PMID 38020922, 2023). "Rubiarbonol-B (Ru-B), a natural arborinane triterpenoid extracted from Rubia philippinesis, switches apoptosis to necroptosis by upregulation of RIPK1 phosphorylation and NOX-1-derived ROS generation in colorectal cancer cells." (PMID 36361505, 2022). "The receptor-interacting protein kinase 1 (RIPK1) is an important signal molecule in the pathway of cell survival, apoptosis, and necrosis, which is significantly upregulated in colorectal cancer (CRC) cells." (PMID 35743109, 2022). "Additionally, organoid models have been used to explore the regulation of RIPK1 by the fragile X mental retardation protein (FMRP) and its role in colorectal cancer resistance to necroptosis." (PMID 40427552, 2025). "We performed western blotting experiments on colorectal cancer cells transiently and stably transfected with TRAF6 plasmids, and we found that the levels of RIPK1 and p-RIPK1 proteins in colorectal cancer cells that highly expressed TRAF6 protein were significantly reduced." (PMID 36604411, 2023). "To confirm whether TRAF6 could induce tumor progression through the inhibition of necroptosis in colorectal cancer cells through the RIPK1-RIPK3-MLKL axis, we co-transfected TRAF6 and RIPK1 into SW480 cells." (PMID 36604411, 2023). "The recent study demonstrated that TRAF6 promotes colorectal cell progression by inhibiting the RIPK1/RIPK3/MLKL necroptosis signaling pathway, which may provide a new therapeutic target for colorectal cancer." (PMID 36604411, 2023). "Furthermore, downregulated RIPK1 and RIPK3 expression has been documented in colorectal cancer tissues versus normal tissues, and thus, their reduced expressions impair cancer cells’ responses to necroptosis stimulation." (PMID 36361505, 2022). "The receptor-interacting protein kinase 1 (RIPK1), taking part in cell survival/apoptosis pathways, was recently shown to bind MCU for the mitochondrial Ca2+ uptake induction and thus contribute to the development of colorectal cancer." (PMID 31569359, 2019). "Furthermore, in colorectal cancer organoid models, the suppression of FMRP, which regulates necroptosis through its interaction with RIPK1 mRNA, led to spontaneous cell death, suggesting that modulating FMRP could promote necroptosis and improve chemotherapy outcomes in chemoresistant cells." (PMID 40427552, 2025). "Consequently, we observe minimal or no reduction in RIPK1 canonical splicing of exon 4 to exon 5, or in resistance to necroptosis, upon PTBP1 knockout in the human colorectal cancer cell lines." (PMID 29449584, 2018).
rheumatoid arthritis (27 papers, 2017 to 2025). A chronic, systemic autoimmune disorder characterized by inflammation in the synovial membranes and articular surfaces. "RIPK1 inhibitors have been advanced into multiple of human clinical studies beyond Phase I including for the treatment of rheumatoid arthritis and Crohn’s disease." (PMID 34689152, 2021). "Notably, several RIPK1 inhibitors are currently under clinical evaluation for the treatment of rheumatoid arthritis." (PMID 41214720, 2025). "This multicenter, randomized, double-blind (sponsor-unblinded), placebo-controlled, experimental medicine study evaluated the safety, pharmacokinetics (PK), and preliminary efficacy of GSK2982772, a RIPK1 inhibitor, in moderate to severe rheumatoid arthritis (RA)." (PMID 33726834, 2021). "RIPK1 inhibitors have been advanced into human clinical studies for the treatment of human inflammatory and degenerative diseases including inflammatory bowel diseases, rheumatoid arthritis, psoriasis, ALS and AD." (PMID 34689152, 2021). "However, targeting, for example, the RIPK1 pathway with GSK2982772 in rheumatoid arthritis showed decrease production of MMP3 compared with the placebo group and may be a potential avenue for treatment in cGVHD." (PMID 37526081, 2023). "RIPK1 inhibitors such as GSK2982772 and GSK3145095 are currently evaluated in several clinical trials in rheumatoid arthritis (NCT02858492), psoriasis (NCT02776033), ulcerative colitis (NCT02903966) and cancer (NCT03681951) (Clinicaltrials.gov)." (PMID 31766571, 2019). "To expand our tissue target engagement analysis beyond skin samples, we evaluated RIPK1 target engagement in colon and synovial tissues, as these tissues are the major sites of inflammation in TNF‐dependent diseases such as ulcerative colitis and rheumatoid arthritis, respectively." (PMID 29226625, 2017).